ITLN1 (intelectin 1)
Diseases named in the same sentence as ITLN1 in open-access papers (continued):
Sharing a sentence is not in itself a finding about the gene and the disease.
colitis (3 papers, 2022 to 2025). Inflammation of the colon. "We propose that ITLN1, through direct spatial regulation of a mucus-degrading microbe, makes the host susceptible to colitis." (PMID 36413219, 2023). "Pharmacological inhibition of ITLN1 significantly mitigated epithelial damage and colitis both in vivo and in vitro, establishing ITLN1-targeted therapies and PANoptosis modulation as viable clinical strategies for CD treatment." (PMID 40520022, 2025). "Additionally, the in vivo function of ITLN1 regulation on inflammation, PANoptosis, and the intestinal mucosal barrier was explored in interleukin-10 knockout (IL-10 KO) colitis model mice." (PMID 40520022, 2025). "ITLN1, whose expression is regulated by the unfolded protein response, coats a subset of microorganisms, including Akkermansia muciniphila, allows them to thin the inner mucus layer, and increases colitis severity." (PMID 36413219, 2023). "Colitis severity was similar in SPF Itln1−/− mice colitis and wild-type littermates." (PMID 36413219, 2023). "Overexpression of ITLN1, as occurs in patients with UC, increased the vulnerability of the TgVil1-Itln1 mice to chemically induced colitis and T cell–mediated colitis, consistent with the known role of bacterial penetration of the mucus barrier in predisposing to intestinal inflammation." (PMID 36413219, 2023). "Targeting the ITLN1/CAPN2 axis reduced inflammation and PANoptosis significantly and restored mucosal barrier integrity in colitis models, thereby establishing a basis for subsequent clinical application." (PMID 40520022, 2025). "Together, these results suggest that Itln1, a Paneth cell product in C57BL/6N mice, likely plays a minor role in the pathophysiology of chemically induced colitis." (PMID 36072603, 2022). "We investigated the response of Itln1 knockout mice to challenge with DSS, a common model of chemically induced colitis in mice." (PMID 36072603, 2022).
colon adenocarcinoma (3 papers, 2010 to 2015). "In opposition to MPM, colon adenocarcinoma cells lost expression of intelectin-1, and the Caco-2 colon adenocarcinoma cell lines did not secrete intelectin-1." (PMID 20628387, 2010). "Based on the high ITLN1 levels in colon adenocarcinoma, it is plausible to speculate the involvement of ITLN1 in gastrointestinal malignancies." (PMID 25965823, 2015). "Intelectin-1 was detected in the cytoplasm of normal colonic goblet cells but not that of colon adenocarcinomas." (PMID 20628387, 2010).
Pleural effusion (3 papers, 2010 to 2015). The presence of an excessive amount of fluid in the pleural cavity. "Thus, intelectin-1 in pleural effusion could be used as a specific and stable diagnostic marker for MPM." (PMID 20628387, 2010). "In this study, we analysed intelectin-1 produced by MPM cells and measured intelectin-1 concentrations in pleural effusions or plasmas of MPM patients." (PMID 20628387, 2010). "Trimeric intelectin-1 (120 kDa) was detected in plasma and pleural effusion of all MPM patients on western blotting." (PMID 20628387, 2010). "Most pleural effusions contained larger amounts of intelectin-1 than plasma." (PMID 20628387, 2010). "Most pleural effusions of patients with other diseases contained <1000 ng ml−1 of intelectin-1." (PMID 20628387, 2010). "In this study, we investigated whether intelectin-1 was specifically contained in MPM cells and the pleural effusion of MPM patient by immunohistochemistry, western blotting, and enzyme-linked immunosorbent assay." (PMID 20628387, 2010). "Intelectin-1 was not proteolysed at 37 °C for 24 h in plasma or pleural effusion." (PMID 20628387, 2010). "The amount of intelectin-1 in the plasma of MPM patients was inconsistent and did not correlate with that of the pleural effusion." (PMID 20628387, 2010). "Half of the pleural effusions of MPM patients (Y2, Y4, and Y7), but not patients with other diseases, contained >3000 ng ml−1 of intelectin-1." (PMID 20628387, 2010).
ulcerative colitis (3 papers, 2021 to 2025). An inflammatory bowel disease involving the mucosal surface of the large intestine and rectum. "Intelectin-1 (ITLN1) is a lectin secreted by intestinal epithelial cells (IECs) and upregulated in human ulcerative colitis (UC)." (PMID 36413219, 2023). "Of note, ITLN1 expression in the colon was elevated (p < 0.05) in specimens from individuals diagnosed with ulcerative colitis." (PMID 34145348, 2021). "Furthermore, ITLN1 has been identified as a potential genetic risk factor for IBD, with significantly elevated expression in ulcerative colitis (UC), possibly participating in UC pathogenesis by disrupting the intestinal mucus barrier and microbiota homeostasis." (PMID 40520022, 2025).
Barrett esophagus (2 papers, 2018 to 2025). Esophageal lesion lined with columnar metaplastic epithelium which is flat or villiform. "Applying transcriptomics or advanced immunohistochemistry along the esophageal epithelium (from normal mucosa through Barrett’s metaplasia to carcinoma) could map which cell types express ITLN1 and how this varies with disease stage." (PMID 41149627, 2025). "Additionally, SPINK4 and ITLN1 mark cells that precede morphologically identifiable goblet cells in colon and Barrett’s oesophagus, potentially aiding the identification of metaplasia." (PMID 30323168, 2018). "In contrast, studies of esophageal adenocarcinoma have positioned ITLN1 not as a dynamic biomarker of progression, but rather as a stable marker of Barrett’s esophagus (BE), the metaplastic precursor lesion." (PMID 41149627, 2025).
Cachexia (2 papers, 2020 to 2022). Severe weight loss, wasting of muscle, loss of appetite, and general debility related to a chronic disease. "Future mechanistic studies are important to evaluate the effects of VAT in cachexia and in particular the role of Itln1." (PMID 32232960, 2020). "Moreover, cluster 10, annotated as mesothelium originated progenitor cells with specific expression of ITLN1 and MSLN, was almost exclusively found in VAT in non-cachexia patients." (PMID 36376273, 2022).
Cirrhosis (2 papers, 2023 to 2025). A chronic disorder of the liver in which liver tissue becomes scarred and is partially replaced by regenerative nodules and fibrotic tissue resulting in loss of liver function. "Low expression of ITLN-1 was associated with a larger tumor volume, poor pathological differentiation, vascular invasion, incomplete capsule and occurrence of cirrhosis." (PMID 38050235, 2023). "Univariate Cox regression analysis showed that the risk of death and recurrence in HCC patients increased with tumor size, capsule status, degree of cirrhosis, vascular invasion, and low expression of ITLN-1." (PMID 38050235, 2023). "Our results regarding the correlation between ITLN1 and cirrhosis, vascular invasion, and tumor size provided clinical evidence of the correlation between ITLN1 and HCC progression, although the strength of this evidence may need to be further validated in more HCC cohorts." (PMID 41218553, 2025). "Furthermore, in Tongji cohort, there was a negative correlation between ITLN1 expression and tumor size, as well as the risks of cirrhosis and vascular invasion." (PMID 41218553, 2025).
gastrointestinal infection (2 papers, 2013 to 2021). "Human ITLN1 is produced from the goblet cells and secreted into mucus in normal colon epithelia, and expression level of ITLN1 was upregulated during gastrointestinal infection." (PMID 34217290, 2021). "In normal colon epithelia, human ITLN-1 is produced from the goblet cells and secreted into mucus, and the ITLN-1 expression increases during gastrointestinal infection." (PMID 24358121, 2013).
ischemia (2 papers, 2017 to 2019). A hypoperfusion of the BLOOD through an organ or tissue caused by a PATHOLOGIC CONSTRICTION or obstruction of its BLOOD VESSELS, or an absence of BLOOD CIRCULATION. "This is the first study to demonstrate changes in ITLN1 expression in a large cohort of human left ventricular tissue samples following acute ischemia." (PMID 28687077, 2017). "From the same group of patients, 106 paired samples had mean pre-ischemia and post-ischemia ITLN1 plasma levels of 32.23 ± 15.22 and 37.46 ± 16.84 ng/ml respectively." (PMID 28687077, 2017). "We show that pre-ischemia levels of ITLN1 expression in the human myocardium are much higher than the nominal levels depicted in the GTEX consortium." (PMID 28687077, 2017). "mRNA expression of ITLN1 decreases in left ventricular tissue after acute ischemia in human patients (mean difference 280.48, p = 0.001) whereas plasma protein levels of ITLN1 increase (mean difference 5.24, p < 0.001)." (PMID 28687077, 2017). "This is the first study to demonstrate an acute decline in left ventricular ITLN1 expression following ischemia in a large cohort of surgical patients." (PMID 28687077, 2017). "We next investigated the correlation between pre-ischemia and post-ischemia ITLN1 expression in the left ventricle and clinical parameters using univariate linear regression models." (PMID 28687077, 2017). "Those patients in the prior study with ACS likely had chronic levels of ischemia prior to presentation, and that may have been the driving force behind lower levels of ITLN1." (PMID 28687077, 2017). "As a result, chronic levels of low grade ischemia, as present in patients with CAD, may lead to low levels of plasma ITLN1, but acute ischemia may cause an abrupt increase." (PMID 28687077, 2017).
liver cancer (2 papers, 2023 to 2025). An epithelial or non-epithelial malignant neoplasm that arises from the liver. "The loss of ITLN-1 expression plays an important role in the proliferation, occurrence and development of liver cancer, and is an independent prognostic factor for OS and disease-free survival." (PMID 38050235, 2023). "Real-time fluorescence quantitative polymerase chain reaction was used to investigate 149 liver cancer cases for ITLN-1 mRNA expression." (PMID 38050235, 2023). "However, the relationship between ITLN-1 and the pathogenesis of HCC, as well as whether ITLN-1 can be used as a therapeutic target for liver cancer still needs further study." (PMID 38050235, 2023). "In order to verify the expression of ITLN-1 mRNA in liver cancer tissues, we quantified the expression of ITLN-1 in 149 liver cancer tissues and matched non-tumor tissues by RT-PCR and IHC." (PMID 38050235, 2023).
renal cell carcinoma (2 papers, 2012 to 2022). "Circulating ITLN1 was also lower in patients with renal cell carcinoma than in matched controls." (PMID 35186726, 2022).
Abdominal obesity (1 paper, 2018). Excessive fat around the stomach and abdomen. "The aim of this study was to quantify the association of Val109Asp polymorphism of intelectin 1 (ITLN1) gene with the abdominal obesity (AO) in Kyrgyz population." (PMID 29482534, 2018).
acute coronary syndrome (1 paper, 2017). Signs and symptoms related to acute ischemia of the myocardium secondary to coronary artery disease. "One group showed that patients with acute coronary syndrome (ACS) have lower levels of plasma ITLN1 than healthy controls." (PMID 28687077, 2017).
acute myocardial infarction (1 paper, 2020). Necrosis of the myocardium, as a result of interruption of the blood supply to the area. "The ITLN1-encoded circulating protein, Omentin 1, has a recognized role in cardiovascular disease as a “protective adipokine” able to ameliorate heart damage and function in patients with acute myocardial infarction and in mice models of I/R injury." (PMID 31924244, 2020).
alcohol abuse (1 paper, 2021). The use of alcoholic beverages to excess, either on individual occasions ("binge drinking") or as a regular practice. "The present findings demonstrated that chronic alcohol abuse modified the expression of genes ITLN1 and CFTR in WT mice intestines with minor changes in TLR4-KO compared to the untreated control mice." (PMID 34884634, 2021).
aneurysm (1 paper, 2023). Bulging or ballooning in an area of an artery secondary to arterial wall weakening. "ITLN1 has been reported to be differentially expressed in aneurysm tissue compared to control superficial temporal artery tissue, indicating it may be related to IA-lesion specific signaling at the IA site." (PMID 36836499, 2023).
breast invasive carcinoma (1 paper, 2025). "LEPR shows differential expression among breast invasive carcinoma stages, while ITLN1 shows differential expression in stage II only." (PMID 41221514, 2025).
cardiomyopathy (1 paper, 2017). A disease of the heart muscle or myocardium proper. "A small number of other genes were regulated inversely in different adult forms of cardiomyopathy (RCM/DCM or RCM/ICM datasets) relative to RCM, including intelectin 1 (ITLN1), delta-like 1 homolog (DLK1), reelin (RELN), and myosin light chain kinase family, member 4 (MYLK4)." (PMID 28098235, 2017).
coronary artery disease (1 paper, 2017). "With respect to cardiovascular disease, ITLN1 is decreased in metabolic syndrome patients with carotid atherosclerosis along with patients with coronary artery disease (CAD)." (PMID 28687077, 2017).
Crohn's colitis (1 paper, 2025). Crohn's disease affecting the colon. "This study elucidates a pathogenic pathway in which ITLN1 competitively binds TRIM8 to inhibit CAPN2 ubiquitination and degradation, stabilizing CAPN2 to promote ZBP1-mediated PANoptosis in IECs and exacerbate Crohn's colitis." (PMID 40520022, 2025).
dysplasia (1 paper, 2018). A usually neoplastic transformation of the cell, associated with altered architectural tissue patterns. "In 30 BO endoscopic mucosal resection (EMR) specimens (from 16 patients) with intestinal metaplasia but no dysplasia present, we also consistently observed cells expressing ITLN1 or SPINK4 without MUC2." (PMID 30323168, 2018). "Specifically, quantification of triple immunofluorescence staining of eight BO EMR specimens with intestinal metaplasia but no dysplasia taken from five patients showed 41% of MUC2 low cells expressed SPINK4 and/or ITLN1, whereas 28% of cells expressed MUC2 alone." (PMID 30323168, 2018).
gastric atrophy (1 paper, 2022). "Previously, it has been found that the upregulation of ITLN1 is associated with GC onset in humans, and that downregulation of CHIA causes gastric atrophy." (PMID 35426084, 2022).
gynecological cancers (1 paper, 2022). "In summary, despite the fact that only a limited amount of data were available, a tendency for lower circulating ITLN1 levels in breast and gynecological cancers was observed." (PMID 35186726, 2022). "Several studies assessed the relationship between ITLN1 and gynecological cancers." (PMID 35186726, 2022). "Conversely, women with breast and gynecological cancer expressed less ITLN1 as opposed to healthy individuals." (PMID 35186726, 2022).
heart failure (1 paper, 2025). Inability of the heart to pump blood at an adequate rate to meet tissue metabolic requirements. "Violin plots illustrating inter-subpopulation disparities indicated that C0 NAP1L1+ TCs and C2 MKI67+ TCs possessed considerably elevated heart failure scores, whereas C1 CA2+ TCs demonstrated moderate values, and C3 ITLN1+ TCs displayed the lowest scores." (PMID 40842994, 2025).
hepatic disease (1 paper, 2015). "These genes encode for omentin (intelectin 1), claudin 1, polycystic kidney and hepatic disease 1 (autosomal recessive)-like 1, and annexin A8." (PMID 26636677, 2015).
human papillomavirus infection (1 paper, 2025). "Notably, ITLN1+ fibroblasts in metastatic tissues showed significant enrichment of upregulated pathways, including those related to human papillomavirus infection and lysosomal activity, indicating their involvement in metastatic niche remodeling." (PMID 41246350, 2025).
hypertrophic cardiomyopathy (1 paper, 2025). A condition in which the myocardium is hypertrophied without an obvious cause. "Altered DNA methylation profile was observed in hypertrophic cardiomyopathy which affected altered genes such as ITLN1 related to immune function where ESR1 gene is at its node." (PMID 40406098, 2025).
ileitis (1 paper, 2022). "Alternatively, C57 congenic models, including SHIP-/- (B6.129S6(C)-Inpp5dtm1.1Wgk/J) mice, which develop segmented, transmural ileitis due to perturbations in intestinal T cell immunity, present an opportunity to study Itln1 in isolation." (PMID 36072603, 2022).
intestinal cancer (1 paper, 2022). "Furthermore, genetic models of neoplasia on a C57 background (e.g., C57BL/6J-ApcMin/J mice) may serve as better models than AOM-DSS to study the potential role of Itln1 in intestinal cancer." (PMID 36072603, 2022).
ischemic stroke (1 paper, 2024). A stroke disorder caused by obstruction of blood flow to the brain, due to thrombotic (local blood clot formation) or embolic (due to a blood clot or other material traveling from another site) event. "Association between ITLN1 polymorphisms and ischemic stroke risk in the case-control groups stratified by gender." (PMID 38529304, 2024). "Association between ITLN1 polymorphisms and ischemic stroke risk in the case-control groups stratified by age." (PMID 38529304, 2024). "The association between ITLN1 polymorphisms and ischemic stroke risk." (PMID 38529304, 2024).
metastatic tumors (1 paper, 2025). "ITLN1+ fibroblasts were nearly absent in precancerous and adjacent normal tissues, but specifically appeared in primary and metastatic tumors." (PMID 41246350, 2025).
mucositis (1 paper, 2024). Mucositis is inflammation and damage of the mucous membranes lining the mouth and other parts of the gastrointestinal (GI) tract. "We acknowledge the limitations of this study, including its uncertainty regarding a mechanism by which ITLN-1 contributes to mucositis observed during in vitro and in vivo mucus plugging." (PMID 38724552, 2024).
myocardial ischemia (1 paper, 2017). A disorder of cardiac function caused by insufficient blood flow to the muscle tissue of the heart. "The purpose of this study is to discern the relationship between the expression pattern of ITLN1 RNA in the human heart and the level of circulating ITLN1 protein in plasma from the same patients following myocardial ischemia." (PMID 28687077, 2017). "Nevertheless, the low variance in CKMB levels in our study does not refute other studies that have shown a potential protective effect of ITLN1 towards myocardial ischemia." (PMID 28687077, 2017). "Therefore, we sought to determine the effects of myocardial ischemia on the expression of ITLN1 in the human left ventricle and circulating levels of ITLN1 protein in a large population of patients." (PMID 28687077, 2017).
non-alcoholic fatty liver disease (1 paper, 2025). "Moreover, in previous studies on non-alcoholic fatty liver disease, ITLN1 was shown to preserve protective autophagy through normalization of AMPKα/mTOR signaling, thereby alleviating cellular stress and lipid accumulation." (PMID 41218553, 2025).
Osteopenia (1 paper, 2022). Osteopenia is a term to define bone density that is not normal but also not as low as osteoporosis. "A study exploring the frequency of polymorphism 326A/T of gene ITLN-1 has shown that women with osteoporosis and osteopenia homozygous for AA genotype may lead to lower BMD." (PMID 36531488, 2022). "A logistic regression analysis was performed to ascertain the effects of serum visfatin, Intelectin-1, chemerin, alkaline phosphatase, calcium and phosphate on the likelihood that participants have low BMD (osteopenia and osteoporosis)." (PMID 36531488, 2022).
osteoporosis (1 paper, 2022). A condition of reduced bone mass, with decreased cortical thickness and a decrease in the number and size of the trabeculae of cancellous bone (but normal chemical composition), resulting in increased fracture incidence. "Similar to our findings, a study found increase in levels of Intelectin-1 in postmenopausal women with osteoporosis and labelled it as a postmenopausal physiological compensation against bone loss." (PMID 36531488, 2022).